NLRP3 (NLR family pyrin domain containing 3)
Diseases named in the same sentence as NLRP3 in open-access papers (continued):
Sharing a sentence is not in itself a finding about the gene and the disease.
tumor (continued). "In vivo, adoptive transfer of NLRP3-deficient macrophages increased tumor growth and metastasis and reduced intratumoral CD3+CD8+ T-cell infiltration (all p < 0.05)." (PMID 41140697, 2025). "The inflammasome and in particular its constituent NLRP3 have been implicated in -tumor progression." (PMID 40759978, 2025). "High NLRP3 expression was associated with larger tumor diameters (>2 cm), muscle invasion, and metastasis." (PMID 39144184, 2024). "The Nod-Like Receptor with a Pyrin Domain 3 (NLRP3) is one of the inflammasomes that has been implicated in tumour progression but its role in OC is not well understood." (PMID 39516433, 2024). "It is therefore likely that NLRP3 is activated through other mechanisms, such as the cellular stress caused by the chronic inflammation following bacterial invasion to the tumor microenvironment, that needs to be investigated further." (PMID 38898209, 2024). "Several reports indicated that the TAM-associated NLRP3 activation enhances both tumor development and progression." (PMID 39230586, 2024). "This review aims to summarise probable genes linked to the NLRP3 inflammasome associated with OC to identify its role in tumour progression." (PMID 39516433, 2024). "Certain harmful bacteria, such as Porphyromonas gingivalis and Fusobacterium nucleatum, are specifically implicated in sustaining irritation and tumor progression through pathways including NF-κB and NLRP3 inflammasome." (PMID 39409925, 2024). "Our current study revealed that a high NLRP3 protein level was associated with larger tumor diameters (>2 cm), muscle invasion, and metastasis." (PMID 39144184, 2024). "It has been demonstrated that cancer cells undergoing epithelial-mesenchymal transition (EMT), a hallmark of cancer, suppress NLRP3 inflammasome activities of tumor-associated macrophages (TAMs) in response to chemotherapy." (PMID 38540172, 2024). "NLRP3 is considered an important intermediator between stressful stimuli and inflammatory responses, and its deregulation has been implicated in tumor progression." (PMID 38903927, 2024). "Prior investigation revealed that the NLRP3 inflammasomal suppression using genetic deficiency or pharmacological inhibitor substantially suppresses the metastatic potential of tumor cells." (PMID 39230586, 2024). "Further, severe liver metastasis was observed in mice with Nlrp3-deficient macrophages, which proved that Nlrp3 is involved in regulating tumor-resident microbiota in the TME." (PMID 38890429, 2024). "Secondly, damaged or juxtaposed TAMs release DAMPs to bind tumour cell‐associated receptors, leading to lysosomal disruption, ROS release and K+ efflux in tumour cells, followed by activation of NLRP3 inflammatory vesicles." (PMID 38652105, 2024). "Nevertheless, the complex signaling networks associated with the NLRP3-mediated regulation of tumor angiogenesis and lymphangiogenesis via TAMs requires further elucidation." (PMID 39230586, 2024). "Our current study assessed NLRP3 expression in BC tissue specimens for association with tumor progression and then explored the inflammatory microenvironment in BC progression using LPS stimulation." (PMID 39144184, 2024). "It has been postulated that NLRP3 signaling within tumor-associated macrophages (TAMs) drives the polarization of CD4+ T cells in the tumor microenvironment toward an immune-suppressive phenotype." (PMID 38018872, 2023). "When the intracellular HO-1 expression level is high, pyroptosis-associated NLRP3 expression is inhibited Therefore, the inhibition of HO-1 expression is the key to inducing pyroptotic cell death in tumor cells." (PMID 37092860, 2023). "As well as encouraging myeloid cells, especially MDSC, and TAMs, to enter the TME, NLRP3 is implicated in tumor lymphangiogenesis and lung metastasis." (PMID 37300757, 2023).
tumor (continued). "For tumor associated macrophages (TAMs), whose NLRP3-pyroptosis pathway drives cancer cells to proliferate, accurate therapeutic interventions that specifically target pyroptosis in cancer cells should be considered." (PMID 37891577, 2023). "Activation of the NLRP3 inflammasome causes abnormal secretion of soluble cytokines, resulting in a favorable inflammatory environment that promotes tumor growth." (PMID 37715239, 2023). "NLRP3 expression and IL-1β secretion of BC tumors promote myeloid-derived suppressor cell (MDSCs) and tumor-associated macrophage (TAM) infiltration to the tumor microenvironment and facilitate an inflammatory microenvironment for cancer progression." (PMID 36902278, 2023). "A pan-cancer analysis of twenty-four different tumor cell lines representing several different tissue types found that, in the majority of cell lines examined, NLRP3 and its associated components were in fact downregulated as compared to normal tissues." (PMID 37289257, 2023). "•NLRP3 and MDSCs were increased in fatty liver grafts associated with a higher rate of tumour recurrence." (PMID 37916155, 2023). "NLRP3 activation in tumor-associated macrophages can regulate their polarization, which increases lung metastasis of PDAC32." (PMID 36890219, 2023). "S1PR1 on tumor-associated macrophages promotes lymphangiogenesis and tumor metastasis in breast cancer patients through the NLRP3/IL-1 pathway." (PMID 37803421, 2023). "The programmed cell death (PCD) model of pyroptosis leads to a release of intracellular pro-inflammatory mediators, causing inflammation and promoting tumor progression, a process known to involve the NLRP3 inflammasome." (PMID 37081882, 2023). "In a lung brain metastasis xenograft model, Nlrp3 and Il1b transcripts were upregulated in tumor-associated macrophages, suggesting possible inflammasome activation." (PMID 37749707, 2023). "In contrast, although Nigericin causes initial tumor cell death in tumor cell lines with strong NLRP3 activation and IL-1β and IL-18 production, cells recover and tumors remain active." (PMID 37715239, 2023). "Next, associations between NLRP3 polymorphism genotype frequencies and tumor pathological characteristics were assessed in the CC patient cohort." (PMID 37885032, 2023). "TNFAIP3 is a CRC tumor suppressor but NLRP3 level is associated with poorer survival in patients with aggressive CRC and chronic intestinal inflammation, such as IBD, is considered a risk factor for the development of colorectal cancer." (PMID 37081882, 2023). "Mechanistically, HDM caused a particular subtype of CLI, in which the NLRP3/IL-1β signaling pathway is chronically activated in macrophages, and made the lung microenvironment conducive to tumor development." (PMID 36670473, 2023). "Conversely, a high expression of NLRP3 inflammasome‐related genes was associated with increased CM overall survival and higher tumor immune infiltration of B cells, CD8+ T cells, and neutrophils." (PMID 36707938, 2023). "Recent studies suggest that activation of the NLRP3 inflammasome and the resulting increase in IL-1β production are associated with tumor progression in various types of cancer, including LC." (PMID 36670473, 2023). "Because of its overexpression in tumor areas and its association with larger tumor size, higher histological grade, and positive node and receptor status, the NLRP3 inflammasome appears to be involved in tumor aggressiveness." (PMID 37715239, 2023). "In vivo, tumor-associated NLRP3/IL-1 signaling induces the expansion of myeloid-derived suppressor cells (MDSCs), leading to reduced NK cell activity." (PMID 37081882, 2023). "Overall, these findings indicate an important role of NLRP3 in the suppression of anti-tumor immune responses and tumor development, associated with a major rewiring of the MDSC compartment." (PMID 36032139, 2022).
tumor (continued). "In a non-small cell lung cancer model, the use of eat-clearing and detoxifying herbs reduced NLRP3 and CyclinD1 expression, causing cellular proliferation and a decrease in tumor growth." (PMID 35745570, 2022). "It was suggested that activation of the NLRP3 inflammasome complex (associated KGs: FN1) would be an innovative therapeutic pathway to control tumor growth." (PMID 35617355, 2022). "Herein, we demonstrate that Nlrp3 deficiency led to diminished tumor development, which was accompanied by a robust anti-tumor immunity and re-arrangement of the MDSC compartment." (PMID 36032139, 2022). "Specifically, for innate immune cells, NLRP3 expression was significantly positively correlated with almost all markers of monocytes, tumor-associated macrophages (TAMs), M2 macrophages, neutrophils, and dendritic cells (all r > 0.5, p < 0.0001)." (PMID 36541912, 2022). "Regarding the G-MDSCs, differential expression analysis revealed 1,521 DEGs (|FC| > 1.5, FDR< 0.05) between tumor-bearing Nlrp3-deficient and WT mice, with 466 and 1,055 genes to be up- and downregulated, respectively." (PMID 36032139, 2022). "Specifically, Nlrp3-deficient mice exhibited reduced tumor growth compared to wild-type animals and induction of robust anti-tumor immunity, accompanied by re-wiring of the MDSC compartment." (PMID 36032139, 2022). "Tumor-associated NLRP3/IL-1β signaling gives rise to an immunosuppressive environment characterized partly by the regulation of M2-polarized TAMs and a reduction in antitumor CD8+ T cells." (PMID 36376979, 2022). "In this instance, virally triggered ATL showed susceptibility to NLRP3 activation, which mediates anti-tumor response." (PMID 35897704, 2022). "To examine the functional importance of NLRP3 pathway during tumor development, we utilized the Nlrp3-deficient mice (Nlrp3-/-), in which the Nlrp3 gene has been disrupted by the insertion of an EGFP cassette." (PMID 36032139, 2022). "While the abundance of evidence indicating its significance in CIN and CIH imply NLRP3 to be a fascinating target for protective therapy, suppression of NLRP3 has also been associated with increased tumour resistance to cisplatin." (PMID 35806229, 2022). "For example, NLRP3 is widely present in tumor cells and is associated with nasopharyngeal cancer, colorectal cancer, and lung adenocarcinoma." (PMID 35883480, 2022). "We used the CD68 marker to stain the amount of tumor-associated macrophages and the IL-1β as a signal for the NLRP3 inflammasone activation." (PMID 35884397, 2022). "Natural products have been shown to activate NLRP3 by increasing ROS levels in tumour cells, which activates Caspase1, causing GSDMD to be cleaved and pyroptosis to occur." (PMID 36105214, 2022). "NLRP3 inflammasome is a kind of cytoplasmic protein complex, which has been proven that it can recruit myeloid-derived suppressor cells (MDSCs) and tumor-associated macrophages (TAMs) to promote tumor progression and metastasis." (PMID 35664314, 2022). "Inhibition of NLRP3 inflammation in macrophages by celastrol is associated with inhibition of tumor cell metastasis." (PMID 33534121, 2021). "NLRP3-deficient tumors exhibit significantly lower tumor growth compared to growth of native B16F10 cells." (PMID 33649199, 2021). "Lower tumor heterogeneity and purity, which suggest the lower proportions of subclonal mutations and tumor cells in microenvironment, were statistically associated with NLRP3 mutations (Wilcoxon rank-sum test, P = 0.048 and P = 0.022)." (PMID 34747716, 2021). "The NLRP3 inflammasome has been implicated in promoting the progression of several malignancies by influencing the intrinsic invasiveness of the tumor while also promoting the process of epithelial-mesenchymal transition (EMT)." (PMID 34638239, 2021). "Considering the agonist role of IL-1β on MDSCs (24, –26) and the role of these cells in tumor-associated immunosuppression, we assessed the effect of NLRP3 inhibition on MDSCs." (PMID 33649199, 2021).
tumor (continued). "NLRP3 activation in cancer cells and the consequent IL-1β secretion have been associated with transmitting signals that stimulate normal cells within the tumor microenvironment and supply them with growth factors." (PMID 34070682, 2021). "Recently, NOD-, LRR-, and pyrin domain-containing protein 3 (NLRP3) has been implicated in causing MDSCs expansion in tumor-bearing mice." (PMID 35003065, 2021). "We observed that patients with NLRP3 mutations had a significantly higher tumor mutation burden (P < 0.001) and neoantigen burden (P < 0.001)." (PMID 34747716, 2021). "In metastatic melanoma, tumor-associated NLRP3/IL-1β signaling induced expansion of MDSCs, leading to reduced NK and CD8+ T-cell activity concomitant with an increased presence of Treg cells in the primary tumors." (PMID 35003065, 2021). "The evaluation of antitumor immunity via DC vaccination demonstrated that the expression of NLRP3 in the tumor microenvironment promoted the migration of tumor-associated myeloid-derived suppressor cells (MDSCs) to the site of the tumor." (PMID 34571825, 2021). "Conversely, the markedly reduced IL-18 expression in NLRP3-deficient mice results in dramatically increased tumour burden in the colon." (PMID 33918087, 2021). "The NLRP3 inflammasome appears to be involved in tumor aggressiveness, given its overexpression in the tumor areas and its association with greater tumor size, higher histological grade and positive node and receptor status." (PMID 34540671, 2021). "Recent papers have associated NLRP3 activation and IL-1β secretion to tumor growth, invasiveness, relapse and progression." (PMID 34540671, 2021). "A related study reported that Nlrp3-deficient mice also have fewer MDSCs accumulating at the region of the tumor and improved survival upon DC vaccination." (PMID 34571825, 2021). "For example, overproduction of IL-1β resulting from constitutive NLRP3 inflammasome activation caused auto-inflammation and enhanced tumour progression in melanoma." (PMID 33918087, 2021). "Estrogen repressed HCC growth through inhibition of tumor-associated macrophages and the NLRP3 inflammasome." (PMID 34881186, 2021). "In oral squamous cell carcinoma cell lines, NLRP3 inflammasome activation and IL-1β secretion were associated with tumor progression, metastases and infiltration of immune suppressive myeloid cells, such as TAMs and MDSCs into the TME." (PMID 33572196, 2021). "The increased expression of NLRP3 was also associated with tumour growth, invasiveness, metastasis, development of cancer stem cells (CSCs) and their self-renewal in HNSCC121–123." (PMID 33602906, 2021). "In vivo, tumor-associated NLRP3/IL-1 signaling induced expansion of myeloid-derived suppressor cells (MDSCs), leading to reduced natural killer and CD8+ T cell activity concomitant with an increased presence of regulatory T (Treg) cells in the primary tumors." (PMID 33649199, 2021). "The current literature has not reported on receptor alterations or dysregulation; nevertheless, NLRP3 has been associated with sending signals to stimulate normal cells within the tumor-associated stroma and supply them with growth factors." (PMID 33613533, 2020). "Colitis-associated cancer was higher in NLRP3 knockout mice models; the increased tumor burden was correlated with attenuated levels of tumor IL-1β and IL-18." (PMID 31923221, 2020). "NLRP3 inflammasome activation and IL-1β secretion play a critical role in promoting tumor growth and metastasis in BC and they are associated with tumor proliferation, angiogenesis, invasiveness, relapse and progression." (PMID 33014808, 2020). "The NLRP3/IL-1β pathway is required for the deleterious effects of 5-FU and gemcitabine on tumor immune response, as tumor growth is inhibited in mice deficient for NLRP3, or IL-1R." (PMID 32635472, 2020). "IL‐1β secretion is a marker of NLRP3 activation, which linked the tissue damages with tumor‐promoting inflammation." (PMID 32508035, 2020).
tumor (continued). "Mechanistically, the groups showed an association of the PD-L1/NLRP3 inflammasome pathway to the recruitment of MDSCs into the tumour tissue causing impairment of the anti-tumour response." (PMID 33116132, 2020). "In different murine cancer models, the association of blocking Abs against CD39 and PD-1 slows tumor growth through a NLRP3/IL-18-dependent and IL-1β-independent mechanism." (PMID 33261061, 2020). "Not only does cancer NLRP3 play a role in adaptive immunity in enforcing immune surveillance, but it also mediates anti-tumor immunity in innate immunity through activation of tumor-associated neutrophils (TAN)." (PMID 33613533, 2020). "In another report, LPS/S1PR1 signaling participates in NLRP3 expression and IL-1β production in tumor-associated macrophages." (PMID 32695095, 2020). "In this context, the P2RX7/NLRP3 pathway is essential, as the anti-tumor effect of oxaliplatin is lost in mice deficient in these proteins." (PMID 32635472, 2020). "S1P was shown to selectively promote the expression of NLRP3 among inflammasome components downstream of S1PR1 in tumor-associated macrophages (TAM), as well as LPS-stimulated mouse BMDM and human primary monocyte-derived macrophages." (PMID 31379883, 2019). "It has been well documented that NLRP3 inflammasome was increasingly associated with tumor development, but its role in different cancer was inconsistent." (PMID 30696442, 2019). "Mechanistically, S1PR1 signaling in lymph vessel-associated macrophages induced NLRP3 expression and IL-1β production, which showed direct pro-lymphangiogenic activity, thereby accelerating tumor progression by promoting metastasis." (PMID 31379883, 2019). "The results demonstrate that inhibition of the NLRP3 inflammasome in macrophages by genetic deficiency or a pharmacological inhibitor is linked to suppression of the metastatic potential of tumor cells." (PMID 31439870, 2019). "It is suggested that dying tumor cells release ATP that is sensed by the P2X7 receptor of DCs leading to NLRP3 activation and is associated with chemo-resistant tumor growth." (PMID 30631327, 2018). "Our data suggested that the increased expression of NLRP3 in OSCC was associated with tumor growth and metastasis." (PMID 29716544, 2018). "Upregulated expression of NLRP3 was significantly associated with T stage (P = 0.001) and tumor differentiation (P = 0.010) of OSCC." (PMID 28637493, 2017). "With the 4-NQO-induced tongue squamous carcinoma model (a widely used OSCC model), we demonstrated that deficiency of NLRP3 inflammasome enhanced the anti-tumor effect of 5-FU." (PMID 28637493, 2017). "Overall, these data indicate that the activation of the NLRP3 inflammasome has an important role in functional tumor-associated MDSC induction." (PMID 28732079, 2017). "Asc-deficient mice especially with the absence in myeloid cells exhibited protective effects in tumor development, similar to the phenotype in Nlrp3/Caspase1-deficient mice." (PMID 28360909, 2017). "In this context, the outcome can then be different since in certain experimental settings this activity is protective against cancer development, while in other settings NLRP3 activation and IL-1β secretion are associated to a more malignant tumor phenotype." (PMID 27221966, 2016). "The reduced tumor growth and metastasis in NLRP3 and caspase-1 deficient mice suggest that inflammasome activity influences tumor development." (PMID 27786298, 2016). "NLRP3 deficient mice had reduced tumor growth, which is similar to what we observed in caspase-1 KO mice." (PMID 27786298, 2016). "This increase in survival of Nlrp3−/− mice was associated with a decrease in the number of tumor-associated MDSC." (PMID 24474192, 2014). "So far, a number of inflammasomes have been identified, of them, the NLRP3 inflammasome has been found associated with tumor development, although controversy exists from different models." (PMID 24223129, 2013).